CTLA4 (cytotoxic T-lymphocyte associated protein 4)
Diseases named in the same sentence as CTLA4 in open-access papers (continued):
Sharing a sentence is not in itself a finding about the gene and the disease.
tumor (continued). "In the tumor, RT alone and in combination with CTLA-4 blockade increased eTreg frequencies." (PMID 38349740, 2024). "Arming oncolytic viruses with ICBs by encoding checkpoint inhibitors or antibodies to block PD-L1 or CTLA-4 within the virus itself may yield comparable or even better anti-tumor activity compared to combinations of an oncolytic virus and ICBs." (PMID 39205202, 2024). "Another tool to repress antitumor immune responses is the expression of immunomodulatory proteins like programmed cell death protein 1 (PD-1), cytotoxic T lymphocyte associated protein 4 (CTLA-4) and lymphocyte activation gene 3 (LAG-3) or their respective ligands in the tumor microenvironment." (PMID 39075115, 2024). "Theoretically, combining CTLA-4 and PD-1 blockade therapies is hypothesized to synergistically enhance anti-tumor effects." (PMID 38500876, 2024). "Furthermore, resident immune cells in the tumor microenvironment express higher levels of CTLA-4; Hence, CTLA-4 can be found in malignancies caused by immunosurveillance." (PMID 38191571, 2024). "In conjunction, PD-1siRNA and CTLA-4 siRNA could be delivered to silence the gene expression to enhance tumor recognition, triggering an immune response against the tumor." (PMID 38751938, 2024). "Crucially, anti‐CTLA‐4 combined with STING agonist therapy failed to cause tumor regression in a mouse tumor model established with STING‐deficient B16 tumor cells." (PMID 38525112, 2024). "Furthermore, viral infection can upregulate the expression of immune checkpoint molecules like CTLA-4 and PD-L1, potentially enhancing tumor responsiveness to ICB." (PMID 39420203, 2024). "Moreover, specific antibiotics, including ampicillin, vancomycin, and lincomycin as well as imipenem, are linked with microbiota alterations, which in turn affect anti-CTLA4 therapy and weaken anti-tumor effects." (PMID 38617537, 2024). "Significantly, ICIs, such as cytotoxic T lymphocyte-associated antigen-4 (CTLA4), programmed death protein-1 (PD-1), and its ligand programmed death ligand 1 (PD-L1), have been found to induce lipid peroxidation and ferroptosis in tumor cells." (PMID 38853203, 2024). "In an independent study, anti-CTLA4 Ab was found to enhance the anti-tumor effect by altering the ratio of effector T cell (Teff) to regulatory T cell (Treg) in the tumor microenvironment (TME) in human Fc-gamma receptors (FcγRs)-treated mouse models inoculated with MCA205 cells." (PMID 38398223, 2024). "This is in line with our observations, that immune cells in the TIME of HLA-G high MIBC – especially of evasion phenotype MIBCs- exhibited an upregulation of crucial immune checkpoint proteins like TIGIT, PD-L1, LAG3, and CTLA-4 on tumor cells (PD-L1) and immune cells (all proteins)." (PMID 39469714, 2024). "Functioning as a symmetric tetravalent bifunctional antibody, it binds simultaneously with high affinity to PD-1 and CTLA-4 expressed on tumor-infiltrating lymphocytes (TILs), achieving a co-targeting effect that enhances anti-tumor efficacy while enhancing safety." (PMID 39068460, 2024). "Again, APG‐157 + anti‐CTLA‐4 treatment group demonstrated tumor growth suppression." (PMID 38686626, 2024). "In this study, tumor infiltrating T cells in anti-CTLA4 resistant samples had a significantly increased number of expanded TCR clones as compared to anti-PD1 resistant samples suggesting that such T cells have an increased tumor-reactivity." (PMID 38594286, 2024). "Anti-CTLA-4 Ab exerted its anti-tumor effects in mice transplanted with either KO cell line." (PMID 39106430, 2024). "Anti-CTLA-4, anti-PD-1, and anti-PD-L1 monoclonal antibodies can potentiate tumor immunogenicity." (PMID 39330010, 2024). "The first anti-CTLA-4 2F’-RNA aptamer was reported by Gilboa’s group and they showed that this aptamer could bind CTLA-4 specifically and inhibit CTLA-4 function in vitro and enhance tumor immunity in mice." (PMID 38473398, 2024).
tumor (continued). "This was further supported by tumor weight analysis because the average tumor weight of the triple treatment group was lowest and was significantly different from two other groups by t tests (P < 0.05 vs mHAdLyp.sT and mHAdLyp.sT+anti-CTLA-4)." (PMID 38267626, 2024). "The preferential induction of expression of CD80 may then lead to stronger dampening of the immuno-regulatory function of CTLA-4, then potentiating anti-tumour immune responses." (PMID 39315158, 2024). "Nonetheless, ICI-mediated tumor therapy targeting CTLA-4 is infrequently applied in clinical setting because it shows delayed effects and is sometimes associated with severe side effects, including hepatitis, colitis, and thyroiditis, owing to overactive immune responses." (PMID 39323561, 2024). "This combination sought to improve antitumor effects by inducing virus-mediated tumor cell death and release of tumor antigens, as well as recruiting/maturing/activating antigen-presenting cells through GM-CSF induction while blocking/depleting Tregs via anti-CTLA-4." (PMID 39055561, 2024). "In the tumor microvironment, tumor cells may inhibit the T cell responses by secret the immunosuppressive proteins that bind with the CTLA‐4 and PD‐1, shows to be a central target of immunosuppression in the therapeutic antitumor immunity." (PMID 38270295, 2024). "In an EMT-6 mammary carcinoma model IL-21 and mAb CTLA-4 combination therapy induced complete regression in half of the mice and noticeable delays in tumor growth for the rest of mice employed in the study, while the combination of IL-21 and mAb PD-1 displayed no noticeable effects." (PMID 38638431, 2024). "CTLA-4 negatively regulates Treg cell activation against tumor-associated antigens (TAAs) by interacting with their ligands, B7.1 and B7.2, with higher affinity compared to CD28 binding to these ligands, and downregulates immune response against tumor." (PMID 38255322, 2024). "Among the immune escape mechanisms, the upregulation of immune checkpoints like cytotoxic T-lymphocyte antigen 4 (CTLA-4) in lymphoid organs and PD-1/PD-L1 in peripheral tumor tissues is the most well-studied tumor escape mechanism in many tumor types, including NSCLC." (PMID 39001412, 2024). "Immune checkpoint inhibitors (ICIs) reinvigorate anti-tumor immune responses by disrupting co-inhibitory immune checkpoint molecules such as programmed cell death 1 (PD-1) and cytotoxic T lymphocyte antigen 4 (CTLA-4)." (PMID 39247203, 2024). "In addition to CTLA-4, programmed death-1 (PD-1) is another inhibitory receptor on T-cells, while PD-L1 is its ligand, which is expressed on tumour cells." (PMID 39336171, 2024). "Notably, the combination of anti-CD47 Ab and anti-CTLA4 Ab resulted in a more substantial delay in tumor growth than either of the single-agent treatments." (PMID 38398223, 2024). "Additionally, Bacteroides fragilis can promote the maturation of DCs and augment the IL-12-dependent Th1 cell immune response, thereby amplifying the anti-tumor efficacy of anti-CTLA-4 treatment." (PMID 38617841, 2024). "Consistently, Vanpouille-Box and co-workers revealed that delivering 24 Gy in three fractions of 8 Gy promotes DC recruitment and CTL infiltration through IFN-β secretion and cGAS-STING pathway activation, enabling synergistic tumour rejection with CTLA-4 blockade therapy." (PMID 39450176, 2024). "At this point of the discussion, it is worth commenting/postulating that the CTLA-4 c.-1577G>A SNV can alter the survival of CM patients treated only with surgical tumor resection and conventional chemotherapy, as seen in our cases, possibly due to deregulation of the immune system." (PMID 39596391, 2024). "Moreover, currently available ICB antibodies aiming to enhance tumor cell recognition by lymphocytes and T cell cytotoxicity, such as anti-PD-1, anti-PD-L1, and anti-CTLA-4, have shown great promise in clinical use53." (PMID 38167274, 2024).
tumor (continued). "In addition, TF is comparable to CTLA‐4 or PD‐1 antibodies used alone for increasing T cell infiltration and promoting tumor cell apoptosis, while the combination of TF and CTLA‐4 antibodies is more effective." (PMID 38938284, 2024). "Enhanced CD80 expression on TISCs might engage with inhibitory CTLA4 on T cells, resulting in immunosuppression and tumor progression." (PMID 38891044, 2024). "Immune cells in tumor-draining lymph nodes and tumor-infiltrating lymphocytes from mice treated with IR and anti-CTLA4 demonstrated an upregulation of genes in T-cell functions and enrichment in both CD4+ and CD8+ T-cell populations compared to mice given IR and the isotype control." (PMID 39199612, 2024). "Furthermore, they showed that their nanovaccine synergized with a checkpoint blockade (anti-CTLA-4 + anti-PD-L1 cocktail) to block tumor growth in B16F10 melanoma and CT26 colon cancer mouse models." (PMID 38391959, 2024). "We hypothesized that adding activation of innate immune cells with anti-CD40 + CpG to the RT + IC + anti-CTLA-4 combination would provide an additional pathway to enable greater anti-tumor efficacy." (PMID 38731089, 2024). "Importantly, STLNPs-Man@mRNA possessed the ability to downregulate cytotoxic T lymphocyte-associated antigen-4 (CTLA-4) expression by blocking the CD206/CD45 axis, showing enhanced anti-tumor efficacy through combined immune checkpoint blockade therapy." (PMID 39066365, 2024). "Recently, the mostly used checkpoint inhibitors (ICIs), which include CTLA-4 and programmed cell death protein 1 (PD-1)/PD-L1 inhibitors acting through reversing the immunological signals from the immunosuppressive tumour microenvironment, have attracted significant attention in OC oncotherapeutics." (PMID 38892471, 2024). "Tumor mutational burden was associated with response to a combination of immune checkpoint inhibition with anti-CTLA4 and anti-PD1 but did not have a statistically significant association with progression-free survival on anti-PD1 monotherapy." (PMID 38611025, 2024). "Next, we examined the role of IFN-g produced by Th1 on tumor elimination by anti-CTLA-4 Ab." (PMID 39106430, 2024). "IPS is defined based on tumor immune infiltration characteristics and bridges immune cell infiltration with immunogen subtypes, which can forecast the response to immunotherapy strategies including CTLA4 and PD-1 inhibitors." (PMID 39074262, 2024). "Blimp1-deficient Tfr cells exhibit impaired inhibitory activity and reduced production of Foxp3, CTLA-4, and other cytokines, contributing to inhibit interactions with Tfh cells and B cells and promote anti-tumor immunity, and these destabilized Tfr cells convert to Tfh-like cells." (PMID 39227959, 2024). "Furthermore, the inhibition of PD-L1 and CTLA4 in CD155−/− mice resulted in strongly increased anti-tumour effects compared to those of PD-L1/CTLA4 blockade in WT mice." (PMID 38893071, 2024). "Taken together, these data suggest that chronic HS treatment upregulated TGFβ-mediated immune exhaustion, leading to tumor progression, and the combination of immune checkpoint inhibitor therapy (anti-CTLA4 mAb) with anti-TGFβ mAb is more efficient at reducing tumor progression." (PMID 38891044, 2024). "Through the inhibition of cytotoxic T lymphocyte-associated protein-4 (CTLA-4), programmed cell death protein-1 (PD-1), and programmed cell death 1 ligand-1 (PD-L1), ICIs bolster the host’s immune system to effectively recognize and target tumor cells." (PMID 39621799, 2024). "Immune checkpoint inhibitors (ICIs) work by inhibiting the interaction between immune checkpoints, such as PD-1 and CTLA-4, and their ligands, thus preventing the immune escape of tumor cells, boosting the activity of T cells, and improving anti-tumor immune memory." (PMID 39220648, 2024).
tumor (continued). "Despite this activation, the presence of inhibitory molecules including PD‐1 and CTLA4 on the surface of T‐cells, overexpression of their respective ligands by tumor cells, and interaction with DAMP‐activated dendritic cells all work in tandem to suppress T‐cell function." (PMID 39526426, 2024). "CTLA-4 blockade efficacy is known to largely rely on a high CTL over Treg ratio in the tumor." (PMID 38349740, 2024). "However, the anti-CTLA-4 Ab possibly exhibits anti-tumor effects through multiple mechanisms that depend on the specific experimental conditions." (PMID 39106430, 2024). "Since the efficacy of checkpoint therapy is linked to the neoantigen load and NU7441 increased neoantigen expression, we investigated the ability for NU-SL40 to enhance the antitumor activity of combination treatment with anti–PD-1/–CTLA-4 in mice bearing an established B16-F10 tumor." (PMID 39436696, 2024). "Therefore, blocking the immune checkpoint B7/CTLA‐4 enhances the activation of tumor‐specific T cells." (PMID 39158178, 2024). "CTLA-4 acts on tumor tissues and peripheral circulation, whereas PD-1/PD-L1 acts only on the tumor." (PMID 38434964, 2024). "ICB drugs such as anti‐CTLA4/LAG3/TIGIT antibodies may be effective considering their high expression on tumor reactive T cells." (PMID 39136172, 2024). "Immunocompetent mouse models with a triple negative breast tumor (4T1) when treated with GRID and antibodies against immune checkpoints PD1 and CTLA-4 showed that a systemic immune activation to a primary tumor, can promote anti-tumor immune responses outside the radiation field." (PMID 38033759, 2024). "In addition, mutations of several genes involved in the response to IFN-γ in tumor cells render them resistant to certain therapies (e.g., anti-CTLA-4 therapy)." (PMID 38247871, 2024). "Thus, the TC-1 tumor promoted priming of thymus-derived Tregs in the TdLN, and RT, alone and in combination with CTLA-4 blockade, further supported this process." (PMID 38349740, 2024). "A significant component of the TME in CHL is cytotoxic T-lymphocyte-associated protein 4 (CTLA-4), a regulatory molecule that can inhibit the immune response, therefore decreasing the ability of the immune system to destroy tumour cells and is related to tumour aggressiveness." (PMID 38978137, 2024). "Immunotherapeutic approaches aim to tip this balance in favour of anti-tumour immunity by targeting Treg activation or inhibitory pathways such as the programmed cell death protein 1 (PD-1), its ligands (PD-L1 and PD-L2) or CTLA-4." (PMID 38610929, 2024). "The idea of triple therapy combining anti-PD1/PD-L1 with anti-CTLA4 and an OV has recently become very attractive, with a study in which an Ad in combination with anti-PD-L1 and anti-CTLA4 significantly inhibited tumor growth and prolonged survival in a TNBC orthotopic mouse model." (PMID 38256250, 2024). "Similarly, a paralogue-specific Hsp90 inhibitor synergizes with anti-PD1/anti-CTLA4 checkpoint inhibitor therapy in mice and results in a dramatic reduction in tumour size with a concomitant increase in survival." (PMID 38645275, 2024). "In tumour Treg cells, both anti-TIGIT isotypes drove downregulation of immunosuppressive and Treg-cell-associated genes such as Il10, Ctla4 and Tnfrsf1b relative to treatment with anti-PD-L1 antibodies or control, and sustained those effects in combination with anti-PD-L1." (PMID 38418879, 2024). "However, tumor cells evade immune attack by expressing inhibitory immune checkpoint receptors such as PD-1, CTLA-4, and LAG-3, as well as regulatory T cell immune suppressive molecules like TGF-β and IL-10." (PMID 38415252, 2024). "Consequently, reversing human T-cell exhaustion is a crucial mechanism through which patients receiving PD-1 and CTLA-4 pathway drugs achieve significant anti-tumor effects." (PMID 39146202, 2024).
tumor (continued). "Furthermore, the integration of CD47 blockade, MET inhibitors, and anti-CTLA-4 therapy engages both the innate and adaptive immune systems, enhancing phagocytosis, reducing tumor growth, and strengthening immune responses." (PMID 39275127, 2024). "Hence, anti-CTLA-4, anti-PD-1, and anti-PD-L1 can bind these co-inhibitory receptors, reactivating the immune response against tumor cells." (PMID 37801695, 2024). "Among these pathways, the programmed death-ligand 1 (PD-L1)/programmed cell death protein 1 (PD-1) axis and cytotoxic T-lymphocyte-associated protein 4 (CTLA-4) pathway have garnered significant attention due to their roles in immune evasion and tumor progression." (PMID 38785789, 2024). "We found that the combination of MerTK ASO with radiotherapy and anti-PD1 or anti-CTLA4 significantly enhances the anti-tumor immune response and improves treatment efficacy in both the primay, irradiated tumors and secondary, unirradiated tumors in an anti-PD1-resistant lung cancer model." (PMID 38443968, 2024). "Within tumour CD4+ Treg cells, IgG2b and IgG2a anti-TIGIT antibodies reduced the expression of genes associated with suppressive capacity, including Tigit, Ccr8 and Ctla4." (PMID 38418879, 2024). "Thus, PD-1/PD-L1 like LAG-3 inhibition acts directly at the tumor site, whereas CTLA-4 inhibition acts mainly during T cell priming when antigen-presenting cells (APC) and the T cells interact in lymph nodes." (PMID 39518012, 2024). "Indeed, deleting CTLA-4 in Tregs leads to widespread lymphocyte proliferation, fatal autoimmune diseases, heightened IgE production in mice, and robust tumor immunity." (PMID 39684559, 2024). "However, the use of GVAX/MQ in combination with anti-CTLA-4 achieved the best overall survival results, with ∼80% tumor-free mice at 100 d post treatment." (PMID 37891002, 2024). "As our studies have shown TGFβ-mediated upregulation of CD80 expression following the sequential passaging of tumor cells in the HS cohort, we next studied if the combination of anti-TGFβ monoclonal antibodies (mAbs) with immune the checkpoint inhibitor anti-CTLA4 mAb will impact tumor progression." (PMID 38891044, 2024). "As Ad-CTLA-4 enhanced the immune response and effectiveness of an Adenovirus-based poly epitope vaccination encoding tumor neoantigens, we demonstrated that Ad-CTLA-4’s adjuvant activity is independent of the Vaccine antigen." (PMID 38180994, 2024). "Given the profound association of IL-6 with Th17 cells, recognized as significant contributors to inflammation in colitis or IBD, recent endeavors have sought to incorporate IL-6 blockade alongside dual PD-1 and CTLA-4 blockade to mitigate the irAE and enhance tumor immunity." (PMID 38785789, 2024). "We recently published that a combination of one fraction of 12 Gy RT, srIL-2 and anti-CTLA-4 could induce complete regression of large B78 tumors with tumor volume of 1000 mm3 in about 50% of mice." (PMID 39076988, 2024). "Notably, the impact of CTLA-4 expression on survival appears to vary depending on the tumor location." (PMID 39845973, 2024). "Enterococcus faecium induces synergistic antitumor effects of CTLA4 inhibitors via peptidoglycan fragments, which activate CX3CR1+ monocytes, stimulate cytotoxic lymphocytes to produce granzyme B, and reduce the number of tumor-associated macrophages." (PMID 38715617, 2024). "As mentioned in the preceding paragraphs, tumors promote the formation of highly immunosuppressive TMEs, preventing the generation of effective anti-tumor immune response through multiple mechanisms such as limiting T cell effector functions by engaging PD-1 and CTLA-4." (PMID 39682686, 2024). "Furthermore, combination therapy with Nivolumab and Ipilimumab (CTLA4 inhibitor), showed evident beneficial effects, especially for patients with BRAF-mutated tumours." (PMID 38040818, 2024). "Conversely, CTLA-4 and PD-1 blockade alone are insufficient to suppress tumor growth." (PMID 38956700, 2024).